SPIN1 (spindlin 1)
Description:
Chromatin reader that specifically recognizes and binds histone H3 both trimethylated at 'Lys-4' and 'Lys-9' (H3K4me3K9me3) and is involved in piRNA-mediated retrotransposon silencing during spermatogenesis. Plays a key role in the initiation of the PIWIL4-piRNA pathway, a pathway that directs transposon DNA methylation and silencing in the male embryonic germ cells, by promoting recruitment of DNA methylation machinery to transposons: binds young, but not old, LINE1 transposons, which are specifically marked with H3K4me3K9me3, and promotes the recruitment of PIWIL4 and SPOCD1 to transposons, leading to piRNA-directed DNA methylation (By similarity). Also recognizes and binds histone H3 both trimethylated at 'Lys-4' and asymmetrically dimethylated at 'Arg-8' (H3K4me3 and H3R8me2a) and acts as an activator of Wnt signaling pathway downstream of PRMT2. In case of cancer, promotes cell cancer proliferation via activation of the Wnt signaling pathway. Overexpression induces metaphase arrest and chromosomal instability. Localizes to active rDNA loci and promotes the expression of rRNA genes. May play a role in cell-cycle regulation during the transition from gamete to embryo (By similarity). Involved in oocyte meiotic resumption, a process that takes place before ovulation to resume meiosis of oocytes blocked in prophase I: may act by regulating maternal transcripts to control meiotic resumption (By similarity).
Synonyms: SPIN; TDRD24
Tractability: Small molecule: a structure with a bound ligand is known; a high-quality ligand is known. PROTAC: UniProt records ubiquitination sites on it; ubiquitination databases record sites on it; its protein half-life has been measured; a small molecule that binds it is known.
Target class: Reader; Epigenetic regulator
Chemical probes: EML631 (high quality), VinSpinIn (high quality)
Gene: Protein-coding gene on chromosome 9 (88,387,434 to 88,480,234, forward strand). Ensembl gene ENSG00000106723.
Subcellular location: Nucleus; Nucleus, nucleolus
Subcellular location (Human Protein Atlas): Nucleoplasm
Gene Ontology:
Molecular function: histone H3K4me3 reader activity; histone reader activity; protein binding
Biological process: positive regulation of DNA-templated transcription; positive regulation of Wnt signaling pathway; rRNA transcription; protein localization to chromatin; regulation of DNA-templated transcription; transposable element silencing by piRNA-mediated DNA methylation; gamete generation
Cellular component: nucleolus; nucleoplasm; nucleus; chromatin; spindle
Genetic constraint (gnomAD): Loss-of-function variants: 2 observed, 24.87 expected, observed/expected ratio (o/e) 0.0804, 90% interval 0.032 to 0.25. The upper end of that interval is the gene's LOEUF score, 0.25, which puts it in group 1 of 6, group 1 being the genes least tolerant of losing a copy. Missense variants: 124 observed, 335.62 expected, observed/expected ratio (o/e) 0.37, 90% interval 0.32 to 0.43. Synonymous variants: 101 observed, 121.31 expected, observed/expected ratio (o/e) 0.83, 90% interval 0.71 to 0.98.
Homologues: Orthologues: chimpanzee SPIN1 (100% identical), macaque SPIN1 (100% identical), rabbit SPIN1 (100% identical), mouse Spin1 (99% identical), pig SPIN1 (99% identical), rat Spin1 (98% identical), dog SPIN1 (97% identical), tropical clawed frog spin1 (94% identical), guinea pig SPIN1 (93% identical), rat Spin1 (87% identical), zebrafish spina (85% identical), zebrafish spinb (55% identical). Paralogues in human: SPIN3 (83% identical), SPIN2B (77% identical), SPIN2A (77% identical), SPIN4 (71% identical).
Diseases named in the same sentence as SPIN1 in open-access papers:
SPIN1 is named in the same sentence as 42 diseases in open-access papers, as found by Europe PMC text mining. Sharing a sentence is not in itself a finding about the gene and the disease. The quoted sentences say what the papers report.
breast cancer (17 papers, 2017 to 2025). A primary or metastatic malignant neoplasm involving the breast. "In this study, by ectopic expression and loss-of-function experiments of SPIN1, we indicated that SPIN1 enhanced Adriamycin resistance of breast cancer cells." (PMID 29743122, 2018). "Notably, SPIN1 has been implicated in the progression of human cancer due to its high expression in various cancers, including prostate cancer, breast cancer, pancreatic cancer, colon cancer, and ovarian cancer." (PMID 38777743, 2024). "Moreover, elevated levels of SPIN1 are associated with poor prognosis in patients with breast cancer, colorectal cancer, and gastric cancer." (PMID 38777743, 2024). "Recent studies have shown that human SPIN1 is upregulated in various types of malignant tumor tissues, including ovarian cancer, liposarcoma, breast cancer, and glioma, and may act as an oncogene that is implicated in tumorigenesis and progression." (PMID 32767629, 2020). "Elevated levels of SPIN1 protein have been observed in various types of cancer, such as prostate cancer, pancreas cancer, breast cancer, colon cancer and ovarian cancer, etc." (PMID 39090319, 2024). "Recently, SPIN1 was found to be negatively regulated by miR-148/152, leading to adriamycin resistance in breast cancer." (PMID 34753384, 2021). "Our results establish that SPIN1, negatively regulated by the miR-148/152 family, enhances Adriamycin resistance in breast cancer via upregulating the expression of drug metabolizing enzymes and drug transporter." (PMID 29743122, 2018). "SPIN1 has been shown to be elevated in chemoresistant and metastatic breast cancer tissues and involved in PI3K/Akt-mediated chemoresistance." (PMID 29743122, 2018). "Altogether these data indicate that the expression of the drug metabolizing enzymes CYP2C8, UGT2B4 and UGT2B17, and transporter ABCB4 was positively regulated by SPIN1 in breast cancer." (PMID 29743122, 2018). "SPIN1 expression in breast cancer cells and tissues was detected by quantitative real-time PCR (qRT-PCR) and immunohistochemistry." (PMID 29743122, 2018). "Our results showed that drug-resistant breast cancer tissues (n = 39) exhibited higher SPIN1 protein levels compared with drug-sensitive tissues (n = 39)." (PMID 29743122, 2018). "We find that SPIN1 increases breast cancer Adriamycin resistance via enhancing the expression of drug metabolizing enzymes and transporter CYP2C8, UGT2B4, UGT2B17 and ABCB4." (PMID 29743122, 2018). "We showed that SPIN1 was significantly elevated in drug-resistant breast cancer cell lines and tissues, compared with the chemosensitive ones." (PMID 29743122, 2018). "Next, we confirmed the correlation between SPIN1 expression and drug response in patients with breast cancer." (PMID 29743122, 2018). "Mechanistically, the miR-148/152 family could directly target SPIN1 and increase Adriamycin sensitivity in breast cancer cells." (PMID 29743122, 2018). "In conclusion, we have presented evidence that SPIN1, a novel target of the miR-148/152 family, is upregulated in drug-resistant breast cancer cells and tissues and confers Adriamycin resistance by upregulating drug metabolizing enzymes and transporter in breast cancer." (PMID 29743122, 2018). "Moreover, elevated expression of SPIN1 was strongly correlated with advanced histological stage, chemoresistance and metastasis in patients with breast cancer." (PMID 29547122, 2018). "Additionally, we determined the potential involvement of SPIN1 in breast cancer chemoresistance based on publicly available data." (PMID 29743122, 2018). "Here, we show that SPIN1 is upregulated in drug-resistant breast cancer cells and tissues." (PMID 29743122, 2018). "SPIN1 enhanced Adriamycin resistance of breast cancer cells in vitro, and downregulation of SPIN1 by miRNA could decrease Adriamycin resistance in vivo." (PMID 29743122, 2018).
breast cancer (continued). "Furthermore, SPIN1 is among the predicted targets and has been previously identified to be repressed by miR-29b-1-5p in breast cancer cell lines." (PMID 30323900, 2018). "Moreover, high expression of SPIN1 or low expression of the miR-148/152 family predicted poorer survival in breast cancer patients." (PMID 29743122, 2018). "Here we show that SPIN1 is highly expressed in drug-resistant breast cancer cells and tissues." (PMID 29743122, 2018). "In addition, high expression of SPIN1 or low expression of the miR-148/152 family predicts poorer survival in patients with breast cancer." (PMID 29743122, 2018). "Here we showed that these drug metabolizing enzymes and transporter were controlled by SPIN1 and involved in breast cancer chemoresistance, which may be potential targets to reverse drug resistance in breast cancer." (PMID 29743122, 2018). "As Wnt/β-catenin and AKT signalling have been found to be aberrantly activated and to play crucial roles in the development and progression of breast cancer, we also analysed the effects of miR-29b-1 overexpression and the possible role of SPIN1 on these pathways." (PMID 28423652, 2017). "Our previous investigation demonstrated that SPIN1 may act as an oncogene in breast cancer." (PMID 32767629, 2020). "We previously showed that the histone code reader SPIN1 may act as an oncogene in breast cancer." (PMID 32767629, 2020). "We have previously found that miR-489 could directly target SPIN1 in breast cancer." (PMID 29743122, 2018). "Additionally, we utilized GOBO to determine the expression of SPIN1 across a panel of commonly used breast cancer cell lines and the analysis also revealed that SPIN1 expression was significantly highly expressed in basal-like or triple-negative breast cancer cells." (PMID 29743122, 2018). "Recently, several studies have defined the oncogenic role of SPIN1 in tumorigenesis and progression in several cancers, such as non-small cell lung cancer (NSCLC), liver cancer, gastric cancer, and breast cancer." (PMID 34753384, 2021). "Moreover numerous targets of miR‐148a‐3p have been identified in breast cancer, including ALCAM, NRP1, SMAD2, and SPIN1, they mainly function in regulating cell growth, metastasis, and adhesion." (PMID 32508020, 2020). "SPIN1 is identified as a novel target of the miR-148/152 family and enhances Adriamycin resistance by regulating drug metabolizing enzymes and transporter CYP2C8, UGT2B4, UGT2B17 and ABCB4 in breast cancer." (PMID 29743122, 2018). "While SPIN1 promoted HeLa and liposarcoma cell proliferation, it did not have any demonstrable impact on breast cancer cell proliferation." (PMID 30197756, 2018). "Similarly, in the GEO dataset GSE18728, breast cancer patients who received neoadjuvant chemotherapy and classified as non-responders displayed marginally higher SPIN1 expression than those classified as responders (P = 0.0655)." (PMID 29743122, 2018). "However, whether the metabolizing enzymes and transporters are under the control of SPIN1 in breast cancer chemoresistance has not yet been defined." (PMID 29743122, 2018).
gastric cancer (7 papers, 2018 to 2025). A primary or metastatic malignant neoplasm involving the stomach. "Association between SPIN1 expression and clinicopathologic factors in 112 primary gastric cancer." (PMID 32767629, 2020). "Increasing evidence has shown that human SPIN1 was frequently overexpressed in multiple malignant tumours, such as colorectal cancer, gastric cancer, glioma, and breast cancer." (PMID 39548064, 2024). "Next, we examined the functional significance of SPIN1-IDR in gastric cancer cell proliferation and xenograft tumor growth in nude mice." (PMID 38777743, 2024). "The results indicated that SPIN1 expression is markedly elevated in human gastric cancer samples compared with normal tissues (n = 619, P < 0.05)." (PMID 32767629, 2020). "Moreover, increased SPIN1 expression enhanced cell growth, invasion and cell cycle progression in gastric cancer cells." (PMID 34753384, 2021). "In addition, elevated SPIN1 expression correlates with poor prognosis in breast, colorectal and gastric cancer patients." (PMID 29547122, 2018). "miR-409 serves as a newly discovered manager in multiple types of cancer which directly targeting radixin to depress tumor cell metastasis and invasion in gastric cancer, also functions as a tumor suppressor in non-small-cell lung cancer (NSCLC) through PI3K/AKT pathway by directly targeting SPIN1." (PMID 32662828, 2020).
liposarcoma (7 papers, 2015 to 2024). A usually painless malignant tumor that arises from adipose tissue. "Similarly, high SPIN1 level was associated with greater malignancy in liposarcoma cells in vitro, and SPIN1 overexpression enhanced cell proliferation and reduced apoptosis through PI3K/AKT signaling." (PMID 30197756, 2018). "Together, our data describe a molecular mechanism for SPIN1 function in liposarcoma and suggest that targeting SPIN1 chromatin association with small molecule inhibitors may represent a novel therapeutic strategy." (PMID 25749382, 2015). "Importantly, a mutation of SPIN1 within the reader domain interfering with chromatin binding reduces liposarcoma cell proliferation and survival." (PMID 25749382, 2015). "The histone code reader Spindlin1 (SPIN1) was shown to impair proliferation and increase apoptosis of liposarcoma cells in vitro and in xenograft mouse models." (PMID 38254762, 2024). "Binding to methylated lysine is required for SPIN1 to promote proliferation and reduce apoptosis in liposarcoma cells." (PMID 30197756, 2018). "We show that SPIN1 is overexpressed in human liposarcoma compared to normal adipose tissue or lipoma." (PMID 25749382, 2015). "High levels of SPIN1 have been observed in liposarcoma (this study) and other types of tumors including ovarian cancer." (PMID 25749382, 2015). "SPIN1 is overexpressed in human liposarcoma compared to normal adipose tissue or lipoma and enhances proliferation and restricts apoptosis of tumor cells." (PMID 25749382, 2015). "To investigate potential cooperation of SPIN1 and MAZ in liposarcoma, we analyzed genome-wide chromatin association of MAZ by ChIP-seq." (PMID 25749382, 2015). "Our data provide evidence that SPIN1 controls liposarcoma cell proliferation and apoptosis by directly enhancing the expression of GDNF, an activator of the RET signaling pathway." (PMID 25749382, 2015). "Here, we show that reducing SPIN1 levels strongly impairs proliferation and increases apoptosis of liposarcoma cells in vitro and in xenograft mouse models." (PMID 25749382, 2015). "Together, these results show that the H3K4me3 reader function of SPIN1 is required to promote cell proliferation and reduce apoptosis of liposarcoma cells." (PMID 25749382, 2015). "In summary, our data demonstrate that SPIN1 controls proliferation and survival of liposarcoma by regulating GDNF expression and thereby RET activation." (PMID 25749382, 2015). "Quantification of 155 patient samples by immune reactive score showed that SPIN1 protein levels correlate with the aggressiveness of liposarcoma." (PMID 25749382, 2015). "To identify transcription factors that mediate the effect of SPIN1 on liposarcoma cell proliferation and apoptosis, we searched for enrichment of transcription factor motifs in the set of 293 differentially expressed direct SPIN1 targets." (PMID 25749382, 2015). "To investigate a potential role of SPIN1 in liposarcoma, we first analyzed proliferation and apoptosis of T778 and MLS1765 cells upon SPIN1 knockdown." (PMID 25749382, 2015). "Recent evidences showed that human Spindlin1 (SPIN1) was highly expressed in ovarian cancer and liposarcoma, and may be implicated in tumorigenesis and development." (PMID 29743122, 2018). "Hence, SPIN1 depletion reduces proliferation and increases apoptosis of tumors derived from liposarcoma cells in vivo." (PMID 25749382, 2015). "Thus, SPIN1 depletion in liposarcoma cell lines results in reduced proliferation and increased apoptosis." (PMID 25749382, 2015). "Furthermore, our analysis of publically available microarray data of liposaroma samples confirmed that SPIN1 mRNA significantly increases with the degree of malignancy of liposarcoma." (PMID 25749382, 2015). "Thus, SPIN1 knockdown reduces liposarcoma cell-derived tumor growth in mice, which correlates with reduced levels of both GDNF mRNA and RET phosphorylation." (PMID 25749382, 2015).
liposarcoma (continued). "Next, we aimed to understand whether the reduced tumor size observed in BALB/c nude mice resulted from decreased proliferation and/or increased apoptosis of SPIN1-depleted liposarcoma cells." (PMID 25749382, 2015). "To identify signaling pathways involved in SPIN1-mediated control of liposarcoma cell proliferation and apoptosis, we analyzed the phosphorylation status of major signaling proteins upon siRNA-mediated knockdown of SPIN1 using a PathScan® RTK Signaling antibody array." (PMID 25749382, 2015). "Importantly, SPIN1-mediated control of target gene transcription, liposarcoma cell proliferation and survival critically depends on binding to H3K4me3 suggesting that targeting this interaction with small molecule inhibitors may be a useful therapeutic approach for cancer treatment." (PMID 25749382, 2015). "Together, these data suggest that MAZ and SPIN1 cooperate to regulate GDNF expression in T778 cells and that MAZ, at least in part, contributes to SPIN1-mediated control of liposarcoma cell proliferation and apoptosis." (PMID 25749382, 2015). "Accordingly, knockdown of SPIN1 or MAZ results in reduced levels of GDNF and activated RET explaining diminished liposarcoma cell proliferation and survival." (PMID 25749382, 2015). "Our mechanistic studies in vitro and in xenograft mouse models demonstrate that SPIN1, in cooperation with the transcription factor MAZ, controls proliferation and apoptosis of liposarcoma cells by directly regulating expression of the RET signaling pathway effector GDNF." (PMID 25749382, 2015). "This idea is in line with our experiments demonstrating that SPIN1, but not SPIN1 F141A, can rescue the effect of SPIN1 depletion on liposarcoma cell proliferation and apoptosis." (PMID 25749382, 2015). "Thus, SPIN1 controls target gene expression, proliferation, and apoptosis by modulating RET signaling in liposarcoma." (PMID 25749382, 2015).
ovarian carcinoma (7 papers, 2015 to 2024). A malignant neoplasm originating from the surface ovarian epithelium. "Furthermore, it has been identified that miR-382-5p can induces apoptosis by targeting PRPF8 and SPIN1 in ovarian cancer and lung cancer, respectively." (PMID 34122108, 2021). "SPIN1, a new member of the SPIN/SSTY family, was originally identified as a highly expressed protein in ovarian cancer." (PMID 29547122, 2018).
non-small cell lung carcinoma (4 papers, 2021 to 2025). A group of at least three distinct histological types of lung cancer, including non-small cell squamous cell carcinoma, adenocarcinoma, and large cell carcinoma. "This axis has been implicated in non-small cell lung cancer progression and radiation resistance, highlighting its potential as a therapeutic vulnerability in SPIN1-high malignancies." (PMID 40567896, 2025). "SPIN1 was shown to be highly expressed in various types of malignant tumors, including ovarian cancer, breast cancer, non-small cell lung cancer, liver cancer, and liposarcoma." (PMID 40567896, 2025). "Previous studies have shown that targeting SPIN1 can enhance the radiosensitivity of non-small cell lung cancer (NSCLC) cells and improve the efficacy of radiotherapy." (PMID 39090319, 2024).